IL10 (interleukin 10)
Diseases named in the same sentence as IL10 in open-access papers (continued):
Sharing a sentence is not in itself a finding about the gene and the disease.
infection (continued). "MHCII+, SCA-1+, and CXC3R1- monocytes can produce prostaglandin E2 (PGE2) and interleukin 10 (IL-10) in the case of infection." (PMID 36361554, 2022). "Cerebral lymphocytes from IL-10-/- mice had higher numbers and percentages of cells expressing TGFβRII compared to cells from WT mice at both 3 and 5 days after infection." (PMID 36016413, 2022). "The presence of IL-10/IFN-γ Tr1 cells has been shown in human infection but it is in mouse models that the production of IL-10 and IFN-γ in Tr1 cells has been shown to be dependent on IL-27 signaling." (PMID 36146602, 2022). "Blocking IL-10 in CBA/J mice during the chronic stage of infection improved control of bacterial load and improved survival." (PMID 36189368, 2022). "The presence of IL-32γ during the infection increased the cardiac levels of IL-10, which were higher in IL-32γTg than in WT mice." (PMID 35097133, 2022). "Skin resident tissue macrophages, which face S. mansoni secretory/excretory products through infection, produce IL-10 in vivo early post-infection with S. mansoni cercariae." (PMID 36362992, 2022). "The anti-inflammatory cytokine IL-10 is produced by CD (+) cells and plays a crucial role in maintaining tissue homeostasis in the presence of infection or inflammation." (PMID 36290210, 2022). "The first identified, Orf virus (ORFV) IL-10, greatly enhanced infection of its host, exhibiting immune modulatory effects equivalent to human IL-10." (PMID 35631028, 2022). "In the lungs, both IL-4 and IL-10 were significantly induced following infection with smooth Brucella spp., but levels were significantly lower with secondary compared to primary infection." (PMID 36032120, 2022). "T cell-derived IL-10 can also act directly on B cells early on in infection, influencing B cell survival, their interactions with Tfh and ultimately the formation of germinal centers." (PMID 36146602, 2022). "The production of IL-10 was only detected at 24 hpi onward, where values obtained for all infections were similar among all strains but higher than those obtained in the control (PMA 100 nM)." (PMID 35873160, 2022). "While IL-10 can be produced by both macrophages and T cells, IL-10 production by macrophages during M.tb infection occurs early in the infection, but later production of IL-10 by T cells predominates." (PMID 36189368, 2022). "The cytokines IFN-γ, TNF-α, IL-10, and IL-17 were also measured in the homogenate of the heart after 28 days of infection." (PMID 35097133, 2022). "It would be worth exploring the effects of alcohol on these cells, both in their secretion of IL-10 and in their ability to repel infection." (PMID 36105802, 2022). "For instance, in a study using L. braziliensis strains, inoculation of BALB/c mice by a strain indicated a higher ratio of IFN- /IL-10 than another strain, which was measured in their LN cells, at 3 and 15 days after the infection." (PMID 35090305, 2022). "Day of euthanasia also significantly influenced all targets except Cox1; relative to placentae from mice infected at E6.5 (i.e., E15.5), transcripts for Ifnγ, Tnf, Il1β, Il10, and Cox2 in placentae from E8.5 infections (i.e., E16.5) were all elevated." (PMID 35312688, 2022). "Several pro-inflammatory cytokines, such as TNF-α, IFN-g, TGF-b, and IL-10, were triggered in response to bacteria after infection." (PMID 35369604, 2022). "Previous studies from our laboratory have shown that acute S. Typhimurium infection induces the production of high levels of IL-10 5 days post-infection in the liver and spleen, which correlates with infection severity." (PMID 35739937, 2022). "This study showed mRNA expression of pro-inflammatory cytokines (IFN-γ, TNF-α, and TGF-β1) significantly upregulated in the infection, similar to IL-10, anti-inflammatory agents commonly used to reduce skin injury." (PMID 35369604, 2022).
infection (continued). "Levels of proinflammatory cytokines in Mtb-infected lung lysates, including IL-6 and TNF, were significantly upregulated, while IL-10 levels in the coinfected group were comparable with those in the Mtb-infected group at 7 days post LCMV Arm infection." (PMID 35672321, 2022). "Extrapolation of this physiological MIF/IL-10 model to other pathogens/infections deserves also some caution." (PMID 35464430, 2022). "In the case of SARS-CoV-2, an increase in the concentration of inflammatory cytokines such as IL-1β, IL-2, IL-6, IL-7 and TNF-α comes to the fore, along with the rise in IL-4 and IL-10 concentrations in a later stage of infection." (PMID 36294388, 2022). "This lack of immunity has been partially attributed to the parapoxvirus IL-10, as lesions were substantially reduced during infection and reinfection of sheep with an ORFV in which this gene was deleted." (PMID 35631028, 2022). "IL-10 induces differentiation of monocytes to M2 macrophages, which carry out an anti-inflammatory role marking the clearance of infection and mediating the switch-off of inflammatory response." (PMID 36159650, 2022). "In humans, increased levels of inflammatory cytokines such as IL-6 were found in older males with severe COVID whereas increased levels of anti-inflammatory cytokines like IL-10 were observed in older females 14 days post infection than in males." (PMID 36679892, 2022). "TGFβ and IL-10 work in tandem to strike a balance between Th17 and regulatory T cells, and changes in this balance can determine the outcome of infection." (PMID 36016413, 2022). "The results showed that the levels of IL-4, IFN-γ and TNF-α increased, and the levels of IL-10 decreased after infection with T. gondii." (PMID 36245502, 2022). "In this context, it was observed that MIF suppresses IL-10 production and down-regulates the serum cortisol level during a lethal infection with L. monocytogenes." (PMID 35464430, 2022). "These analyses yielded mechanistic insight into how hIL-10 mediates its many biological effects, while providing a strong indication as to the virulence role that each parapoxvirus IL-10 plays during infection of their respective hosts." (PMID 35631028, 2022). "Compared with the control group, CXCL-1 in the RS218 infection group and DE205B infection group increased 8.62-fold and 5.80-fold and IL-10 increased 5.19-fold and 2.46-fold, respectively." (PMID 36143390, 2022). "It reduces the production of pro-inflammatory factors such as interleukin (IL)-1β and tumor necrosis factor (TNF)-α and increases the production of the anti-inflammatory cytokine IL-10, which results in immunosuppression and worsening of infection." (PMID 36556017, 2022). "On the other hand, negative regulation of inflammatory responses early in infection were linked with cytokine storm, and we found that G, GR, GRY-α and GH-β further have differentially up-regulated expression of Il10." (PMID 36389747, 2022). "We demonstrated in our experiments that inactivation of IL-10 in T cells resulted in reduced virus levels in the intermediate phase of infection." (PMID 36527061, 2022). "Greater numbers and percentages of cells from the brains of IL10-/- mice were positive for phospho-SMAD2/3 on day 3 after NSV infection compared to WT mice." (PMID 36016413, 2022). "The frequency of CD11b- KCs producing TNF-α, even after infection, was very low, while the frequency of cells producing IL-10 increased after infection." (PMID 35720410, 2022). "Most importantly, the anti-inflammatory cytokine IL-10 is a key immunoregulator during infection and is induced in macrophages in vitro when TLR2 signaling is modulated during Candida albicans infection or after exposure to the human pathogenic Yersinia spp." (PMID 35638785, 2022). "A study that used a clone of the Colombian strain, Col cl1.7, demonstrated that this strain induced greater production of IL-10 compared to the infection established by strain Y in monocytes in vitro." (PMID 35069009, 2022).
infection (continued). "IL-10 is an immunomodulatory cytokine that directs immune cell function and restores homeostasis following inflammation and infection." (PMID 35631028, 2022). "Weight gain during infection, cecal lesion score, and the levels of IL-10, an immunosuppressive cytokine important in a variety of mouse models for inflammatory bowel disease, were individually measured." (PMID 35646724, 2022). "IL10 has potent anti-inflammatory and regulatory activities in most immune processes of infection and disease, limiting the immune response to pathogens and thereby preventing damage to the host." (PMID 35898935, 2022). "Similar to the mtDNA levels, the levels of PICs (IL-6, IL-1β, and TNF-α) and IL-10 were consistently downregulated in patients with OmicronS infection." (PMID 36230930, 2022). "The expression levels of IL-10 in the duodenum, jejunum and cecum showed that compared with the blank control group, IL-10 in the infection group was significantly decreased." (PMID 35692296, 2022). "IL-6, CXCL8, and IL-10 mRNA expression induced by ASFV-ΔH240R infection was increased by approximately 5-, 5-, and 10-fold, respectively, compared with ASFV-WT." (PMID 34787458, 2022). "Of note, many reports indicated that the main source of IL-10 in chronic human infections was Foxp3-Th1 cells." (PMID 36359345, 2022). "To test the impact of IL-10 during infection, we disrupted signalling using a blocking antibody against the IL-10R1." (PMID 35428872, 2022). "We further observed that similar to TIM-3 silencing, Btk silencing prevented the increased IL-10 production by BMDCs despite LDPm infection." (PMID 35924848, 2022). "We also observed increased IL-10 levels as infection progressed, from isolated and cultured spleen, MLN and liver cells, with this profile being most evident with anti-CD3 stimulation." (PMID 35958580, 2022). "IL-10 mRNA levels in the intestine showed a significantly higher expression than the control in late infection from 7 to 28 dpi, peaking at 28 dpi." (PMID 36187827, 2022). "The role of IL-10 in modulation of dendritic cell (DC) function early post infection, has been studied." (PMID 36387381, 2022). "This study found that following TTPB, there are significant changes in some inflammatory and infection biomarkers, namely uB2MG, IL-6, IL-8, IL-10 and TNF-α." (PMID 36154663, 2022). "In contrast, the downregulation of IL-10 expression observed in older children would favour less control of parasite multiplication at the beginning of infection and therefore of a higher frequency of parasitaemia in this population than in young people." (PMID 35421083, 2022). "In human peripheral blood mononuclear cells, the production of IL-10 has been evaluated during infection with conidia and yeast cells of S. schenckii." (PMID 35628694, 2022). "Infection of the RPE cells with HCMV Merlin dUL11 GFP showed markedly reduced IL-10 induction in comparison to that induced by the parental virus." (PMID 36445084, 2022). "Compared to the control group, chickens in the M group had increased IL-6, IFN-γ, IL-1β, and IL-10 mRNA expression on days 4, 7, and 10 post-infection (p < 0.05)." (PMID 35875532, 2022). "Although replication kinetics and virus spread and of the two deletion mutants on CCB cells was undistinguishable from wild-type KHV-T (results not shown), differential expression was documented for nfκb, il6, il10 and il1b 48 h after infection." (PMID 36068296, 2022). "Whereas, if the body is in the state of immunosuppression, IL‐10 triggers the necessary biomarkers to activate the pro‐inflammatory response, to curb the infection in the body during infection." (PMID 36176597, 2022). "When evaluating the role of MIF or IL-10 on the course of other infections it is clear from many reports that interfering with either MIF or IL-10 affects differentially the pathogen burden." (PMID 35464430, 2022).
infection (continued). "Four months after the infection and later, we found significantly increased IL10 concentrations (means for Long-COVID0–4 m: 0.84 pg/mL; Long-COVID4–8 m: 0.38 pg/mL)." (PMID 36293090, 2022). "Park & Skerrett had also observed worsening infection in monocytes upon treatment with anti-inflammatory IL-10, even reversing the protective effects of IFN-γ." (PMID 36159650, 2022). "This increase in IL-10 thus serves the double role of inhibiting M1 differentiation and inducing M2 differentiation, allowing the infection to persist." (PMID 36159650, 2022). "Transcriptomics analyses in the hamster model of infection have identified mRNAs for regulatory cytokines (IL-4, IL-10, and IL-21), arginase (Arg1), and low nitric oxide production by macrophages as key factors of immunopathology and parasite persistence." (PMID 35384718, 2022). "The IL-10 production by Tregs increased when patients were newly infected with the virus and was comparable when the infection was resolving." (PMID 36016311, 2022). "Considering that only splenic cells derived from mice infected with C. parapsilosis produced IL-10 and IL-5, in addition to pro-inflammatory cytokines, three days post-infection, we analyzed if this distinct scenario persisted during EAE progression." (PMID 35448617, 2022). "In turn, these regulatory plasma cells alleviate inflammation by dampening microglia activation via IL-10 signalling, limiting pathology, providing novel insights into the mechanisms of B cell-microglia interactions in the brain during infection." (PMID 36180478, 2022). "CD14 downregulation was evident in all the subsets, even though the expression of this marker had already been reduced before infection by the action of IL-10 or TGF-β." (PMID 35215110, 2022). "C. sinensis infection slightly increased levels of serum ALT and AST in Il10+/+ mice at 6 weeks post-infection (wpi)." (PMID 36310865, 2022). "Consider however that IL-10 signaling is also heavily utilized by innate-like B cells, a group important for IgM and as the first line of defense against infection." (PMID 36105802, 2022). "A high TNF to IL‐10 ratio has been reversely correlated to infection outcome in severe burn patients." (PMID 35285058, 2022). "Pro-inflammatory IL-8(CXCL8), regulatory IL-10 and TH-2 type IL-9 cytokines were measured in serum samples of AE patients and infection-free controls using specific ELISA." (PMID 35108275, 2022). "After infection, production of IL-12p40, IL-6 and IL-10 was significantly reduced in AM compared to M1 and M2 macrophages while the production of TNFα was intact." (PMID 36776396, 2022). "IL-10 is a potent anti-inflammatory molecule that regulates excessive production of inflammatory cytokines during an infection or tissue damage." (PMID 35814267, 2022). "Blocking IL-10 increased the cytotoxicity in HCMV Merlin GFP-infected cocultures but not to the extent seen in the presence of HCMV Merlin dUL11 GFP infections, indicating that pUL11 also inhibits cytotoxicity by other, additional mechanisms." (PMID 36445084, 2022). "The key cytokine believed to be involved in parasite survival is IL-10, with IL-10 knockout (KO) mice resistant to infection." (PMID 35335634, 2022). "Compared with the infection group, the level of IL-10 in the JYBR-190 pre-fed, JYBR-190 fed, and antibiotic groups were significantly increased, with the highest level of IL-10 found in the JYBR-190 pre-fed group." (PMID 35692296, 2022). "This study aims to quickly identify bacterial types through IL-6 and IL-10, select appropriate antibiotics in a timely manner, and understand the efficacy of anti-infection treatment through the trends of IL-6 and IL-10." (PMID 35432366, 2022). "infection was correlated to a significant elevation of IL-10 level compared to S. digitata infection." (PMID 36145411, 2022).
infection (continued). "The qPCR data reveal that in the case of IL-10, the expression induced by all serotypes studied was statistically significantly higher compared to the control conditions at both times of infection (p < 0.0001 for all serotypes)." (PMID 35889103, 2022). "Using IL-10 reporter mice, we saw a significant increase in the percentage of CD45+ IL-10+ cells upon infection in the MLN but also in the small intestine lamina propria (SILP)." (PMID 35428872, 2022). "In the MLN, CD4+ T cells were the dominant population of CD45+ IL-10+ cells in both naïve and infected animals, although the proportion of B cells and ILCs within the IL-10+ pool increased slightly upon infection." (PMID 35428872, 2022). "We found that FXR deficiency in hepatocytes promoted the progression of liver injury, aggravated weight loss and death caused by infection, and promoted inflammatory cytokines production, such as IL-6, IL-1β, TNF-α, IL-4, IL-10, and IL-13." (PMID 35930537, 2022). "In the heart and pancreas, CVB3/28 infection induced a strong inflammatory cytokines production, such as IL-10, TNF-α, and MCP-1." (PMID 36016091, 2022). "Differential production of IL-10 is one of the parameters that allow the differentiation of strains after infection." (PMID 35069009, 2022). "R-LD infection results in the NF-κB activation via ligation with TLR2/TLR6, leading to up-regulation of miR-466i in the initial hours of infection, whereas inducing high amounts of IL-10 in late hours." (PMID 35925884, 2022). "Although the infection led to a reduced frequency of IL-10+ cells, up to 60% of the events still produced this cytokine." (PMID 35720410, 2022). "In BMDM cultures pre-conditioned with BEVs prior to an infection-like challenge with LPS, high doses of Bt BEVs significantly upregulated the production of IL-10." (PMID 36439842, 2022). "We observed that infection of Balb/c mice with P. yoelii I 7XL was lethal, and a rapid increase in dynamics of IL-10 producing B220+CD5+CD1d+ regulatory B cells over the course of infection was observed." (PMID 35625397, 2022). "Meanwhile, QKI deficient RAW 264.7 cells showed increased secretion of pro-inflammatory cytokines, such as TNF-α, IL-6, IL-1β, and decreased secretion of IL-10, post-infection." (PMID 36088389, 2022). "As per the literature, the pro-inflammatory cytokines limit the infection, but anti-inflammatory cytokine (IL-10) helps with Leishmania survival inside host macrophages and enhances disease progression." (PMID 36678364, 2022). "Spike-specific T-cells displayed a predominant Type-I cytokine profile, but high IL-10 concentrations were also observed and is noteworthy as this combination has been reported previously as a feature of mild or asymptomatic infection." (PMID 35720281, 2022). "The few reports of HCMV-specific IL-10 CD8+ T cell or regulatory responses have been in patients with other infections such as HIV and HBV, or in liver transplant patients who have progressed to CMV disease, or in ageing studies using a pp65-specific tetramer." (PMID 36558866, 2022). "In the early phase of infection, we observed IL-10 expression predominantly in B cells and myeloid cells in the bone marrow and spleen, whereas dendritic cells and T cells also contributed significantly to the total IL-10 expression in lymph nodes." (PMID 36527061, 2022). "Temporal analyses showed that IL-10 secretion from BMDCs was augmented as early as 6 h after LDPm infection and reached maximum at 24 to 36 h postinfection." (PMID 35924848, 2022). "IL-10 is a potent anti-inflammatory cytokine and is well known as a deleterious cytokine during infection with various pathogens mainly via deactivation of macrophages, resulting in diminished Th1 cytokine production." (PMID 36255321, 2022). "As one of the cytokines overexpressed by M2 macrophages, IL‐10 also has a higher concentration in the late stage of infection." (PMID 36169259, 2022).